CXCR4 (C-X-C motif chemokine receptor 4)
Diseases named in the same sentence as CXCR4 in open-access papers (continued):
Sharing a sentence is not in itself a finding about the gene and the disease.
lymphoma (continued). "Besides high and CXCR4-specific uptake of [64Cu]NOTA-pentixather in the Daudi lymphoma xenograft, some background activity uptake is observed in the liver, the gall bladder, and the intestines." (PMID 29527563, 2017). "Interestingly, the effect of rituximab was enhanced by the C-X-C chemokine receptor type 4 (CXCR4) antagonist plerixafor (AMD3100) in a related type of lymphoma (Burkitt lymphoma)." (PMID 27307990, 2016). "Alongside, a substantially decreased uptake in CXCR4-positive lymphoma xenografts, [68Ga]NOTA-pentixafor also shows enhanced accumulation in the excretory organs, leading to low tumor/background ratios and inferior imaging contrast compared to [68Ga]pentixafor." (PMID 27655427, 2016). "We speculate that the abnormal CXCR4high/CXCL12low condition at the primary sites lead to the dissemination of CXCR4+ lymphoma cells to distant organs expressing higher CXCL12, which resulted in disease progression of CXCR4+ DLBCL." (PMID 25704881, 2015). "A few case reports described the presence of CXCL9 and CXCR3 17, as well as CXCL12 and CXCR4 18, on lymphoma cells and these CXC chemokines may serve as positive regulators for the lymphoma cells to aggregate in specific intravascular space." (PMID 24931821, 2014). "Therefore, we conclude that CXCR4 turnover in qCD4s is truly stable, with a small fraction of CXCR4 slowly recycled, whereas CXCR4 turnover is significantly more rapid in both lymphoma and activated qCD4s." (PMID 24516533, 2014). "Once we showed, that in our lymphoma samples before therapy CXCR4 expression was high and it was comparable to CXCR4 expression in reactive lymph nodes, it can be determined with a large probability that this chemokine receptor is expressed by host microenvironment cells." (PMID 24859274, 2014). "Authors suggested the role of CXCR4 in hematogenous lymphoma dissemination." (PMID 24859274, 2014). "Treatment with the CXCR4 antagonist, AMD3100, has been shown to enhance antibody-mediated cell death in disseminated lymphoma models, suggesting a potential role for CXCR4 antagonists in combination with a B-cell targeted therapy in the treatment of B-cell malignancies in the clinical setting." (PMID 22536253, 2012). "The therapeutic viruses use CD4 and CXCR4 for cell entry and could potentially be used against CXCR4 expressing malignancies such as T-lymphoblastic leukemia/lymphoma, NK leukemia and some myeloid leukemias." (PMID 17005036, 2006). "Additionally, dysregulated CXCR4 expression and a C-terminally truncated constitutive active CXCR4 mutant are major prognostic biomarkers for the relatively indolent lymphomas such as the germinal center B cell type (GCB)-DLBCL and lymphoplasmacytic lymphoma (LPL) or WM, respectively." (PMID 40076664, 2025). "In addition, the herein described missing lymphoma-sink effect may also be of relevance for dosing studies using novel CXCR4-inhibitory “cold” drugs." (PMID 37286923, 2023). "In addition, the CXCL12/ACKR3/CXCR4 axis was proposed to be involved in lymphoma." (PMID 36713377, 2022). "Thus, decreased expression of CXCR4 in malignant MF cells upon disease progression might facilitate lymphoma cell mobility, or even dissemination." (PMID 34583709, 2021). "However, additional utility for response assessment might be found in CXCR4-directed PET imaging of lymphoma of the central nervous system." (PMID 30105558, 2018). "Furthermore, our protein expression and GEP data suggested that the impact of CXCR4 on lymphoma relapse and progression of de novo DLBCL may be attributed to dysregulations in both the tumor microenvironment and the tumor cells themselves." (PMID 25704881, 2015). "Moreover, it is unknown whether the use of a CXCL12/CXCR4 antagonist in nodal DLBCL will result in lymphoma cell mobilization and increased spreading." (PMID 25704881, 2015).
lymphoma (continued). "This further demonstrated that ACKR3 enhances CXCL12/CXCR4-mediated intercellular-induced lymphoma migration by promoting LTB4 production, revealing the cell-to-cell-induced migration of lymphoma." (PMID 40427609, 2025). "Investigating a potential lymphoma-sink effect on CXCR4-targeted PET/CT for hematological malignancies, we evaluated a cohort of individuals diagnosed with MZL, which presented with a broad range of lymphoma load and in-vivo tracer uptake on PET." (PMID 37286923, 2023). "Our results suggest that 2-AG has a previously unrecognized role in the mobilization of lymphoma cells by effecting the CXCL12-induced migration and the CXCR4 signaling pathways, however, with different effects in MCL compared to CLL." (PMID 36900374, 2023). "The regimen was well tolerated, resulting in CR of all-CXCR4 + lymphoma but the appearance of CXCR- lesions, supporting the use of CXCR4-directed radioligand therapy as a conditioning regimen." (PMID 35303910, 2022). "Recently, nuclear phosphofructokinase, platelet (PFKP) was reported to stimulate CXCR4 expression through c‐MYC activity in T‐ALL and lymphoma cells." (PMID 36054080, 2022). "Studies showed CXCR4 and its ligand CXCL12 to be expressed by lymphoma cells in PVRL, PCNSL and primary testicular lymphoma (PTL)." (PMID 36233057, 2022). "Taken together, our data point to a yet unknown naturally occurring mechanism to dampen CXCR4 activity in WM and the potential to translate these insights into the biology of WM into the development of promising novel therapeutic compounds in this indolent lymphoma subtype." (PMID 33669329, 2021). "Hyperactivated CXCR4 resulted in a more disseminated lymphoma phenotype and accelerated disease in TCL1-driven CLL, while also favoring development of aggressive lymphoma." (PMID 34363012, 2021). "With the encouragement given by previous data on expression of SSTR and CXCR4 in a variety of lymphomas we determined SSTR 2, 3 and 5 and chemokine receptor CXCR4 expression immunohistochemically from tissue samples archived recently in local biobank." (PMID 34307181, 2021). "We observed SSTR2 and CXCR4 immunopositivity in DLBCL, FL and HL in approximately half of the patients and co-expression of both receptors in 38% of the three lymphoma subtypes." (PMID 34307181, 2021). "CXCR4 expression is upregulated in CLL and MCL, affecting migration and homing of malignant B-cells to lymphoma niches." (PMID 32370190, 2020). "The selected genes included 36 genes mutated in at least one of the six OAML studied by WGS and/or at least in two of the eight lymphomas studied by WES, as well as two additional genes (CXCR4, ACTN4)." (PMID 32316399, 2020). "So far, we and other groups have conducted studies investigating the role of CXCR4 in DLBCL, whereby the results mainly pointed toward a prominent role of CXCR4 in lymphoma dissemination." (PMID 31554271, 2019). "In the case of [64Cu]NOTA-pentixather, the overall high stability is also reflected by increasing tumor-to-blood ratios, which, accompanied with its promising CXCR4-targeting properties, resulted in high-contrast PET/CT images of lymphoma xenografts." (PMID 29527563, 2017). "CXCR4 not only is expressed in CLL but also in a variety of cancers including acute myeloid leukemia, myeloma, lymphomas, clear cell renal cell carcinoma, breast, lung, colon, pancreatic, and ovarian cancer." (PMID 26646452, 2016). "Authors proved CXCR4 role in NHL progression and demonstrated, that using CXCR4-antagonist (BKT140) has potent anti-lymphoma activity, by induction of apoptosis." (PMID 24859274, 2014).
lymphoma (continued). "It is noteworthy that both the GBM and lymphoma hybrid transplants all retained CD74, CXCR4 and VIM genes, suggesting that these are important to evaluate in other examples of spontaneous fusions of human tumor and rodent host cells." (PMID 23405135, 2013). "Epigenetic agents and the CXCR4 antagonist Plerixafor, which enhances rituximab-induced cell killing, might also offer potential benefits in managing CD20-negative lymphomas." (PMID 40612965, 2025). "Although significantly lower levels of CD20+CD27+CD24+CD40+CXCR4+CXCR5+ B cells were observed in MC14 of HIV+ pre-NHL (cART-naïve) samples, these cells had a potential pre-lymphoma phenotype as they expressed both cMYC and AICDA compared to HIV+ cART-naïve and HIV-negative samples." (PMID 39324141, 2024). "CXCR4-directed RLT was then also applied to AML and patients with lymphoma." (PMID 37290799, 2023). "We hypothesized that CXCR4, CXCR5, CXCR7 and CD44 are expressed on CD20-positive lymphoma cells in the eyes of this PCNSL PDX model." (PMID 36233057, 2022). "We compared the eyes of a lymphoma PDX model derived from a PCNSL versus SCNSL patient stereotactic CNS biopsy regarding infiltration of human CD20 positive lymphoma cells and immunohistochemical expression of the homing receptors CXCR4, CXCR5, CXCR7 and CD44." (PMID 36233057, 2022). "Interestingly, we did not observe any substantial differences between GC-B and the lymphoma entities for the B-cell homeostatic chemokine receptors, CXCR3, CXCR4, and CXCR5." (PMID 35887224, 2022). "In this study, we detected co-expression of CD20 and CXCR4 on lymphoma cells in the PCNSL group but not in the SCNSL group." (PMID 36233057, 2022). "Therefore, it would be of high interest to study prognosis of lymphomas co-expressing SSTR2 and CXCR4 since the former seems to be a favorable and the latter an unfavorable biomarker." (PMID 34307181, 2021). "The CXCR4-specific high-affinity antagonist BKT140 revealed potent in vivo anti-lymphoma properties that synergise with rituximab, by effectively targeting lymphoma cells in the bone marrow microenvironment and overcoming stroma-induced resistance to rituximab." (PMID 34575965, 2021). "Specific chemokine receptors and adhesion molecules make lymphoma cells capable of “homing in” on certain body sites (e.g., lymph nodes for CCR7 and CXCR4/CXCR5) and this property might be the basis of primary disseminated clinical presentation of lymphoma." (PMID 31947775, 2020). "In order to study the CXCR4 expression with [68Ga]pentixafor PET in different types of non-Hodgkin lymphoma, we performed a retrospective study to describe the [68Ga]pentixafor PET/CT imaging in a spectrum of lymphomas and to compare it with [18F]FDG PET/CT." (PMID 32757068, 2020). "Based on our finding that CXCR4 and CXCL12 are expressed simultaneously on lymphoma cells, it might be speculated that an autocrine stimulation loop occurs in aggressive lymphomas." (PMID 31554271, 2019). "Furthermore, we observed that CXCL12AF647 was bound just via CXCR4 in the BL2, SuDHL4, and U2932 cells, whereas it was additionally bound via CXCR7 in the RI-1 cells, indicating that these two cell lymphoma lines also express CXCR7 on their surface." (PMID 31554271, 2019). "Additionally, the lymphoma cell line BL2, which is known to strongly express CXCR4 and to migrate toward CXCL12 in transwell migration assays, was included." (PMID 31554271, 2019). "Moreover, the role of CXCR4 in DLBCL has also been described and is related to increased dissemination of lymphoma cells and decreased survival of patients." (PMID 29920526, 2018). "As of now, there is only one prospective trial for CXCR4-directed ERT in preparation (COLPRIT trial, Eudra-CT 2015-001817-28), that will primarily investigate the tolerable dose and side effects of such ERT in patients with MM or lymphoma." (PMID 30105558, 2018).
lymphoma (continued). "Importantly, EPI-X4 and its derivatives crossreact to murine Cxcr4, so that the potential of these MSNs can be tested in murine AML and lymphoma models." (PMID 29343865, 2018). "Additionally, a CXCR4 peptide antagonist LY2510924 and BKT140 also showed anti-tumor activities in lymphoma xenograft models." (PMID 26954567, 2016). "Interestingly, these P3 lymphoma cells exhibited higher expression levels of LFA-1 and CXCR4 in comparison to NKX2-3-negative SMZL samples." (PMID 27297662, 2016). "The following 8 diagnostic scan parameters were recorded by each reader: overall scan result, CXCR4 density in lymphoma tissue, extranodal organ involvement, No. of affected extranodal organs and extranodal organ metastases, lymph node (LN) involvement, No. of affected LN areas and LN metastases." (PMID 39090381, 2024). "The following 8 parameters were investigated: overall scan result, CXCR4 density in lymphoma tissue, extranodal organ involvement, No. of affected extranodal organs and extranodal organ metastases, lymph node (LN) involvement and No. of affected LN areas and LN metastases." (PMID 39090381, 2024). "As such, given those recent developments of CXCR4-directed, non-radiolabeled drugs, our findings on a missing lymphoma-sink effect on PET may be of relevance not only for “hot,” but also for “cold” CXCR4 inhibitory therapies, including dosing studies." (PMID 37286923, 2023). "Based on our findings, dose to unaffected organs may not decrease in patients with increasing CXCR4-positive lymphoma load or with elevated PET signal." (PMID 37286923, 2023). "It cannot be completely ruled out that acceleration of lymphoma development might be partially mediated by activated CXCR4 signaling in T cells or other cell types of the tumor microenvironment known to express CXCR4." (PMID 34363012, 2021). "To investigate CXCR4 expression in Eμ-Myc mice as compared to WT and Eμ-TCL1 mice as a possible reason for no additional effects of CXCR4 hyperactivation on survival in the Eμ-Myc lymphoma model, we first measured CXCR4 surface expression in the different genotypes." (PMID 34363012, 2021). "Finally, as there is no standardized evaluation system for SSTR and CXCR4 expression at IHC in lymphomas, we had to develop our own system by adapting some of the varying scoring methods used in earlier studies." (PMID 34307181, 2021). "Since CXCR4 plays a central role in B‐cell homing and cancer cell migration, it is intriguing to speculate that normal albumin levels might be necessary to generate sufficient EPI‐X4 levels to impair lymphoma migration." (PMID 35847697, 2020). "Finally, once we demonstrated the T22-PE24-H6 effectiveness to CXCR4+ lymphoma cells we analyzed its harmlessness in non-affected tissues." (PMID 32373205, 2020). "Hence, we expect that low or even no CXCR4 expression leads to none or low activation of the mentioned pathways, thus leading to a higher therapeutic sensitivity of the lymphoma cells." (PMID 31554271, 2019). "Given the fact that Jurkat cells, which are generally used for the determination of CXCR4 affinity, are not tumorigenic in mice and to ensure comparability of data with previous studies, the Daudi lymphoma model was also used in this study." (PMID 29527563, 2017). "Some CXCR4+ GCB-DLBCLs may represent lymphoma cells arising from CXCR4high centroblasts in the CXCL12-rich dark zone and CXCR4− GCB-DLBCLs may be the transformed CXCR4low centrocytes in the light zone, where B cells interact with follicular dendritic and T helper cells." (PMID 25704881, 2015). "Additionally, we demonstrate that the endogenous peptide inhibitor of the CXCR4 (EPI-X4) derivative JM#21 effectively inhibits CD19-mediated migration enhancement and promotes ADCC, thereby augmenting the therapeutic efficacy of CD19 mAb-based immunotherapy in lymphoma models." (PMID 40076664, 2025).
lymphoma (continued). "No differ in the CXCR4 expression between normal lymphocytes and cancer cells shows, that the change in chemokine receptor expression should not reflect what is the proportion between normal lymphocytes and lymphoma cells, but rather be a reflection of microenvironmental regulation." (PMID 24859274, 2014). "For CXCR4-targeted PET/CT, however, a lymphoma-sink effect has not been determined yet." (PMID 37286923, 2023).
osteosarcoma (107 papers, 2006 to 2025). A usually aggressive malignant bone-forming mesenchymal neoplasm, predominantly affecting adolescents and young adults. "This analysis demonstrated that CXCR4 expression is moderately associated with inferior overall in patients with osteosarcoma." (PMID 39896512, 2025). "Expression level of chemokine receptor- C-X-C motif chemokine receptor 4 (CXCR4) has been well-documented to be strongly associated with osteosarcoma invasion and metastasis." (PMID 34130697, 2021). "Lower levels of the osteosarcoma metastasis-associated proteins CXCR4, MMP-2, MMP-7 and MMP-9 were detected in siEZH2 cells." (PMID 26265454, 2015). "It was determined that CXCR4 (P<0.01) and β-catenin (P<0.05) expression were significantly associated with the clinical Enneking stage, metastasis and survival of osteosarcoma." (PMID 26622806, 2015). "CXCR4 has been implicated in cancer metastases, and it has been confirmed that the expression level of CXCR4 was significantly different in various human osteosarcoma cell lines with different metastatic potentials." (PMID 24618817, 2014). "Previous research has demonstrated CD117+Stro-1+ osteosarcoma cells to be highly metastatic and enriched for a metastasis-associated marker CXCR4." (PMID 24334332, 2013). "In a recent retrospective osteosarcoma patient study, the mRNA expression of the receptors CXCR4, CCR7 and CCR10 by osteosarcoma tissue was linked to clinical outcome." (PMID 18215331, 2008). "On one hand, bone marrow MSCs promote migration and invasion through direct secretion of several cytokines such as C-X-C motif chemokine ligand 12 (CXCL12) that binds to C-X-C motif chemokine receptor 4 (CXCR4) or CXCR7 on osteosarcoma associated with lower overall patient survival." (PMID 31370265, 2019). "Therefore, the present retrospective study was performed to investigate the in vivo expression of CXCR4 and β-catenin in human osteosarcoma, and to analyze the association between the expression of these proteins and clinical prognosis." (PMID 26622806, 2015). "Correlation analysis was performed to determine whether CXCR4 and β-catenin markers were associated with each other in osteosarcoma." (PMID 26622806, 2015). "Furthermore, multivariate analysis identified CXCR4 and β-catenin protein expression levels, as well as clinical stage and metastasis, as significant risk factors for survival in patients with osteosarcoma (P<0.05)." (PMID 26622806, 2015). "CXCR4 expression has been associated with the aggressiveness of osteosarcoma." (PMID 18215331, 2008). "Therefore, CXCR4 expression has been linked to tumor cell invasiveness which is also expressed by osteoblasts and by malignant cells in osteosarcoma." (PMID 31983166, 2020). "Detailed studies using genetically engineered and/or syngeneic murine models of metastatic osteosarcoma are necessary to experimentally elucidate the functional impact of CXCR4 signaling and its candidacy as a therapeutic target in this disease context." (PMID 39896512, 2025). "The CXCR4 antagonist reduced MDSC chemotaxis into the osteosarcoma TME, thereby enhancing the antitumor effects of anti-PD-1 therapy." (PMID 40109854, 2025). "In osteosarcoma, miR-613 has also been shown to suppress CXCR4 expression, thereby driving tumor growth and metastasis to the lungs." (PMID 40549746, 2025). "Activation of the OOCsystem by CXCL12/CXCR4 signaling is associated with heightened OSaggressiveness and accelerated metastasis, as CXCL12/CXCR4 is essentialfor restoring proliferative signaling in osteosarcoma cells." (PMID 41139822, 2025). "Nonetheless, the data from these studies provide intriguing rationale for CXCR4 signaling axis as a viable therapeutic target in metastatic osteosarcoma." (PMID 39896512, 2025). "Taken together, these data highlight both the diversity of CXCR4 signaling and potential clinical utility in metastatic osteosarcoma." (PMID 39896512, 2025).